ALDH1A1 (aldehyde dehydrogenase 1 family member A1)
Diseases named in the same sentence as ALDH1A1 in open-access papers (continued):
Sharing a sentence is not in itself a finding about the gene and the disease.
colorectal cancer (74 papers, 2010 to 2026). A primary or metastatic malignant neoplasm that affects the colon or rectum. "Over-expression of ALDH1A1 is associated with poor prognosis in many cancers such as ovarian, gastric, breast, and colorectal cancers." (PMID 38589907, 2024). "ALDH1A1 expression has been associated with poor differentiation of human colorectal cancer cells and poor patient survival." (PMID 36768694, 2023). "A poorer overall survival rate was shown to be associated with higher levels of ALDH1A1 activity in patients with colorectal cancer even though the expression of ALDH1A1 and A3 in CSCs is assumed to be necessary for ALDH activities." (PMID 36675306, 2023). "ALDH1A1 activity is associated to poor clinical outcome in lung, esophagus, stomach, ovarian, breast and colorectal cancer patients." (PMID 35582039, 2020). "ALDH1 is abundant in tumor samples from patients with CRC, which can be used as a particular marker for CSCs of colorectal cancer, mainly including ALDH1A1, ALDH1B1, and ALDH1A3, are associated with poor prognosis and resistance to chemotherapy in colorectal cancer." (PMID 36387165, 2022). "CRISPR-Cas9-mediated editing led to functional, cellular, and molecular changes confirming the role of ALDH1A1 in colorectal cancer carcinogenesis." (PMID 41631682, 2026). "IHC analysis indicated that colorectal cancer tissues had a positive rate of 94% (63/67) for ALDH1A1 expression." (PMID 36651035, 2023). "The mean ALDEFLUOR-positive rate in 3 colorectal cancer cell lines (LoVo, BE, and HT-29) was 15.5%, and ALDH1A1 displayed high expression in the ALDEFLUOR-positive subpopulation." (PMID 36651035, 2023). "ALDH1A1 is expressed in colorectal carcinomas, and its nuclear expression indicates a favorable prognosis." (PMID 37489188, 2023). "Surprisingly, in the tissue microarray and whole-tissue cohorts, univariate analysis indicated that the cytoplasmic expression of ALDH1A1 cannot be considered a prognostic marker for colorectal cancers." (PMID 35814382, 2022). "ALDH1A1 overexpression evaluated by IHC has been correlated with poor prognosis in many cancers such as lung, ovarian, stomach, breast, and colorectal cancer." (PMID 35582039, 2020). "Our group confirmed the correlation between PrPC and CSC by demonstrating that the levels of PrPC and CSC marker proteins such as Oct4, Nanog, Sox2, and ALDH1A1 significantly increased in human colorectal cancer tissues and colorectal cancer cells." (PMID 33276687, 2020). "In colorectal cancer ALDH1A1 marks cancer stem cells and plays putative roles in tumor progression and drug resistance." (PMID 30308036, 2018). "Here, we have analyzed ALDH1A1 mRNA and protein levels in relation to clinical, histopathological and molecular tumor features in large series of human colorectal cancer." (PMID 30308036, 2018). "In addition, MG cells expressed surface markers of colorectal cancer stem cells (ALDH1A1, CD24, POU5F1, SOX2, and SOX9) to a greater degree compared with non-MG cells." (PMID 31936744, 2020). "Other investigators similarly reported that ALDH is highly expressed in spheroid-derived CSCs of human colorectal cancer (HCT116-SDCSCs) compared with that in parental cells, and that ALDH activity is associated with ALDH1A1 expression and high tumourigenicity." (PMID 32051483, 2020). "ALDH1A1 mRNA levels were analyzed in several large patient cohorts of colorectal cancer." (PMID 30308036, 2018). "Recent global phospho-proteomics analysis studies indeed observed increased phosphorylation at the T267 site on ALDH1A1 in human colorectal cancer and non-small lung cancer tissues; however, the kinase responsible remains unknown." (PMID 28193222, 2017).
colorectal cancer (continued). "Proteins have been proposed as colorectal cancer stem cell markers, including CD133, CD44, ALDH1A1, LGR5 and several others, and these proteins are considered prognostic indicators of CRC." (PMID 34148069, 2021). "Knockout of p53HRmut in SW480 colorectal carcinoma cells resulted in CIC population contraction and reduction of ALDH1A1 expression." (PMID 31974410, 2020). "We have previously demonstrated that ONC201 downregulated CSC markers CD133, ALDH1A1 and CD44 in colorectal cancer cells in vitro and in vivo." (PMID 28767654, 2017). "Stemness markers reported for colorectal cancer stem cells include CD133, CD44, LGR5 and ALDH1A1." (PMID 34148069, 2021). "Among the available colorectal cancer cell lines, HCT116 cells were selected for studying ALDH1B1 enzyme activity because these cells constitutively and highly express ALDH1B1, while they show low ALDH1A1 expression." (PMID 34769507, 2021). "Mechanistically, PCGF1 promotes the expression of the colorectal cancer stemness markers CD133, CD44 and ALDH1A1 by maintaining histone H3K4me3 and removing histone H3K27me3 marks by increasing the expression of the H3K4me3 methyltransferase KMT2A and the H3K27me3 demethylase KDM6A." (PMID 34148069, 2021). "ALDH1A1 and ALDH1B1 were shown to be markers for colorectal cancer." (PMID 32377192, 2020). "By detecting RNA level of LNX1 of the sorted SP and non-SP from the colorectal carcinoma cell line HT29, it was found that LNX1 was highly expressed in SP cells with higher levels of LGR5, ABCB5, ALDH1A1 and CD133 rather than non-SP group." (PMID 29190716, 2017).
pancreatic cancer (65 papers, 2009 to 2026). "Previous studies showed that upregulation of ALDH1A1 expression was associated with enhanced invasiveness in acute myeloid leukemia, nasopharyngeal carcinoma, bladder cancer, and pancreatic cancer." (PMID 28792511, 2017). "In pancreatic cancer patients, ALDH1A1 expression is also implicated in a stem cell marker and correlates with worse outcome." (PMID 24676703, 2014). "ALDH1A1 level and activity are upregulated in patients treated with neoadjuvant chemotherapy and are associated with extreme chemoresistance and poor prognosis in pancreatic cancer and beyond." (PMID 28193222, 2017). "Moreover, increased ALDH1A1 expression was associated with enhanced invasiveness in malignancies such as acute myeloid leukemia, nasopharyngeal carcinoma, bladder cancer, and pancreatic cancer." (PMID 24485040, 2014). "ALDH1A1 activity in cancer has been found to be responsible for resistance to oxazaphosphorines such as cyclophosphamide and is involved in the irreversible oxidization of retinal to retinoic acid (RA), which has been associated with invasion and adhesion in pancreatic cancer cell lines." (PMID 19216797, 2009). "Pancreatic cancer stem cells (PaCSCs) are maintained by specific surface markers (CD44, CD133, EpCAM, ALDH1A1) and regulated by stemness-associated signaling pathways such as Wnt/β-catenin, Notch, Hedgehog, and TGF-β." (PMID 40881675, 2025). "qPCR assay and western blot demonstrated that the expression of ALDH1A1 was upregulated in irradiated pancreatic cancer cells and PDX tumor tissues." (PMID 32228703, 2020). "In pancreatic cancer, RAS-mediated invasion and motility was associated with increased ALDH1A1 expression." (PMID 31208996, 2019). "Negative regulation of ALDH1A1 mRNA transcription by TGF-β through binding of Smad4 to the regulatory sequence of the ALDH1A1 gene reduces both the ALDHbr population and the tumor-initiating activity of pancreatic cancer cells." (PMID 30733805, 2019). "Recently, our study showed that combination of dasatinib and gemcitabine exerts anti-proliferative effects by decreasing the expression of ALDH1A1 in pancreatic cancer MIA PaCa-2 cells with acquired resistance to gemcitabine." (PMID 28671577, 2017). "Both CD24 and ALDH1A1 expression levels were elevated in CTCs compared to leucocytes and pancreatic cancer cell-line cells." (PMID 28569190, 2017). "We observed similar AURKA-mediated positive regulation of ALDH1A1 in Panc1 cells, suggesting that it is a common mechanism in pancreatic cancer cells." (PMID 28193222, 2017). "Recently, increased expression of ALDH1A1 in a pancreatic cancer tissue microarray has been described, and was reported to correlate with a dismal prognosis." (PMID 26783961, 2016). "In contrast, it has been reported that ALDH1A1 expression was a favorable prognostic factor in pancreatic cancer." (PMID 26160842, 2015). "To evaluate if pancreatic cancer cell lines express cancer stem cell markers such as Aldh1 we compared the expression of Aldh1a1 in pancreatic cancer cell lines such as Panc02, 7265PDA and 6606PDA with the liver metastasis cell line 6606l." (PMID 25885700, 2015). "In this study, we investigated the effect of dasatinib on gemcitabine-sensitivity of ALDH1A1-enriched pancreatic cancer MIA PaCa-2 cells." (PMID 24676703, 2014). "Our results suggest that the synergistic antitumor effects of dasatinib/gemcitabine combination are mediated by reducing the level of ALDH1A1 in ALDH1A1-enriched pancreatic cancer MIA PaCa-2 cells." (PMID 24676703, 2014). "Taken together, the present study suggests a potential application of dasatinib/gemcitabine combination to eliminate the CSC population in the ALDH1A1-enriched pancreatic cancer MIA PaCa-2 cell lines." (PMID 24676703, 2014).
pancreatic cancer (continued). "Taken together, targeting of SRC activity by dasatinib or siRNA enhanced gemcitabine-induced cell death by inducting apoptotic cell death and reducing the level of ALDH1A1 expression in ALDH1A1-enriched pancreatic cancer MIA PaCa-2 cells." (PMID 24676703, 2014). "In conclusion, in the present study, we demonstrate a potential significance of ALDH1A1 in two pancreatic cancer cell lines (MIA PaCa-2/P and MIA PaCa-2/GR)." (PMID 22710732, 2012). "In seven pancreatic cancer cell lines and one primary pancreatic epithelial cell line, we assessed the expression of ALDH1A1 by real-time qPCR and Western blotting." (PMID 21708005, 2011). "Immunonhistochemical analysis on whole-mount tissue slides revealed that ALDH1A1 is more abundantly expressed in pancreatic cancer than initially reported by a tissue microarray analysis." (PMID 21708005, 2011). "In summary, our study describes low expression of ALDH1A1 as an independent prognostic marker for a poor clinical outcome in pancreatic cancer on whole-mount tissue slides." (PMID 21708005, 2011). "In pancreatic cancer, the expression of ALDH1A1 was confined to the cellular cytoplasm and occurred in 72 cases (74%), whereas it was negative in 25 cases (26%)." (PMID 21708005, 2011). "Our study demonstrates that high expression of ALDH1A1 is significantly correlated with the proliferation rate of pancreatic tumour cells." (PMID 21708005, 2011). "Recently, ALDH1A1 has been described as a prognostic marker in a pancreatic cancer tissue microarray." (PMID 21708005, 2011). "Immunostaining against ALDH1A1 and Ki-67 was performed on paraffin-embedded samples from 97 patients with pancreatic cancer." (PMID 21708005, 2011). "Intriguingly, this study is the first which identifies low expression of ALDH1A1 as an independent adverse prognostic marker for overall survival in pancreatic cancer." (PMID 21708005, 2011). "Three moderate-poorly differentiated pancreatic cancer samples exhibited lower levels (< 10%) of ALDH1A1." (PMID 19216797, 2009). "Expression of STIP1 and ALDH1A1 in pancreatic tissue was investigated using IHC analysis of pancreatic tumour and normal tissue." (PMID 19216797, 2009). "Elevated expression of STIP1 was observed in pancreatic tumour tissue compared to normal pancreas, whereas ALDH1A1 stained at lower levels in pancreatic tumours, as detected by immunohistochemistry." (PMID 19216797, 2009). "Therefore, the researchers concluded that ALDH1A1 is the major ALDH subtype that determines ALDEFLUOR activity in pancreatic cancer samples." (PMID 36651035, 2023). "Interestingly, dasatinib has been shown to reduce the expression of ALDH1A1, leading to potentiation of gemcitabine in a gemcitabine-resistant pancreatic cancer cell line." (PMID 34207383, 2021). "The expression of ALDH1A1 and ALDH3A1 has also been linked to NRF2 in pancreatic cancer cells." (PMID 34207383, 2021). "As known, ALDH1A1 was one of the most important markers of pancreatic cancer stem-like cells." (PMID 32228703, 2020). "ALDH1A1+ pancreatic cancer cells also showed enhanced HMGA2 expression." (PMID 32228703, 2020). "ALDH1A1 can be useful as a CSC therapy target in cancer tissues that normally express a low level of ALDH1A1, such as breast, lung, colon and gastric epithelium cancer, but not in tissues that normally have high ALDH1A1 expression, such as the liver and pancreatic cancer." (PMID 31728117, 2019). "Silencing of ALDH1A1 enhanced gemcitabine-induced apoptosis in pancreatic cancer cells." (PMID 30166520, 2018). "To examine whether AURKA-mediated regulation of ALDH1A1 was common in other pancreatic cancer cells, we investigated ALDH1A1 subcellular localization in Panc1 cells in the absence or presence of either AURKA shRNA or MLN8237." (PMID 28193222, 2017). "Interestingly, in our previous study, siRNA-mediated ALDH1A1 knockdown inhibited cell proliferation in pancreatic cancer MIA PaCa-2 cells." (PMID 28671577, 2017).
pancreatic cancer (continued). "Thus, targeting AURKA and ALDH1A1 in combination is expected to be highly effective in inhibiting tumorigenesis, chemoresistance, and metastasis in highly lethal pancreatic carcinoma." (PMID 28193222, 2017). "Therefore, to evaluate the role of ALDH1A1 as a prognostic and predictive marker for tumor progression and response to chemotherapy in pancreatic cancer, standardized prospective studies with a larger number of patients are required." (PMID 26783961, 2016). "The presence of aldehyde dehydrogenase positive cells in tumor from patients with pancreatic cancer has been associated with decreased survival, and ALDH1A1 expression (ALDH1A3 was not tested) correlated with invasion of pancreatic cancer cell lines." (PMID 24053169, 2013). "In the present study, we performed experiments to determine whether the direct targeting of ALDH1A1 by small interfering RNA (siRNA) enhances the chemosensitivity of pancreatic cancer cells to GEM." (PMID 22710732, 2012). "Therefore, to evaluate the role of ALDH1A1 as a prognostic and predictive marker for tumour progression and response to chemotherapy in pancreatic cancer, standarised prospective studies with a larger number of patients are required." (PMID 21708005, 2011). "Besides to gynaecological tumours and tumours of the respiratory tract, increased expression of ALDH1A1 in a pancreatic cancer tissue microarray has been recently described to correlate with a dismal prognosis." (PMID 21708005, 2011). "Hence, the aim of our study was to reevaluate the expression pattern of ALDH1A1 in pancreatic cancer on whole-mount tissue slides and to correlate these results with clinical and pathological data." (PMID 21708005, 2011). "Therefore, we performed immunostaining against Ki-67 in consecutive sections and compared the percentage of Ki-67 positive cells with the immunohistochemical score of ALDH1A1 in pancreatic cancer." (PMID 21708005, 2011). "In summary, these data may be helpful for further in vitro studies when assessing the relevance of ALDH1A1 in pancreatic cancer." (PMID 21708005, 2011). "Therefore, we focused on the correlation between the expression of ALDH1A1 and the proliferation rate of tumour cells in pancreatic cancer samples." (PMID 21708005, 2011). "Interestingly, ALDH1A1 was recently shown to mediate cell invasion in pancreatic cancer cells suggesting that it does play a role in cytoskeletal rearrangement." (PMID 19551145, 2009). "We investigated whether the depletion of NRF2 by using small interfering RNAs (siRNAs) is effective in the expression of biomarkers of pancreatic cancer stemness such as aldehyde dehydrogenase 1 family, member A1 (ALDH1A1) and aldehyde dehydrogenase 3 family, member A1 (ALDH3A1)." (PMID 28671577, 2017). "Regulate cluster cell development and stem cell characteristics of pancreatic cancer cells by increasing the expression of DCLK1, POU2F3, ALDH1A1, and IL17RC." (PMID 39906741, 2024). "In the presence of oncogenic KRAS, IL-17 induces transcription of DCLK1 and ALDH1A1 (a marker of embryonic stem cells) through classical pathway activation, and directly upregulates DCLK1 expression in pancreatic cancer cells in a dose-dependent manner." (PMID 39839479, 2024). "Surprisingly, ALDH1A1 also reciprocates and prevents the degradation of AURKA, thereby triggering a positive activation loop that drives highly aggressive phenotypes in pancreatic cancer." (PMID 35814382, 2022). "BMI1, ALDH1A1, CXCR4, EpCAM, OCT-4, c-MYC, and NESTIN are cancer stemness-related markers of pancreatic cancer." (PMID 35806187, 2022). "NRF2-KD abolished the expression of ALDH1A1 and ALDH3A1, leading to sensitization of pancreatic cancer cells to 5-fluorouracil (5-FU)." (PMID 34207383, 2021). "Of importance, NRF2-KD reduces the expression of CSC markers, such as ALDH1A1 and ALDH3A1, in pancreatic cancer cells." (PMID 34207383, 2021).